DKK1 (dickkopf Wnt signaling pathway inhibitor 1)
Diseases named in the same sentence as DKK1 in open-access papers (continued):
Sharing a sentence is not in itself a finding about the gene and the disease.
ankylosis (8 papers, 2012 to 2023). Fixation and immobility of a joint. "Further studies of TNF transgenic mice showed that Dkk-1 blockade led to Wnt pathway activation in sacroiliac joints and, subsequently, to ankylosis, providing strong experimental evidence that the Wnt pathway and specifically Dkk-1 are tightly linked to sacroiliac fusion/ankylosis." (PMID 35743102, 2022). "When DKK1 was blocked, the disease’s phenotype changed from joint damage to remodeling and ankylosis." (PMID 37373903, 2023). "Blockade of DKK-1 has also been shown to drive ankylosis in a TNF-over-expressing mouse model of spondylitis." (PMID 23171658, 2012). "Interestingly, DKK-1 inhibition also leads to a bilateral erosive change and ankylosis of the sacroiliac joints in TNF TG mice, which have symptoms that mimic those of sacroiliitis in humans." (PMID 26634249, 2015). "It has been suggested that continued suppression of inflammation via anti-TNF agents may accelerate new bone formation and ankylosis possibly through upregulation of DKK-1." (PMID 26086874, 2015). "We therefore sought to investigate whether SOST and DKK1 are dysregulated in the PGISp model, given it is a good experimental model for assessing cellular and molecular events involved in severe axial osteoproliferation and ankylosis as seen in AS." (PMID 23171658, 2012). "Furthermore, combined inhibition of DKK-1 and TNF led to a complete abrogation of osteoclast formation and to increased numbers of osteoblasts, bone formation and ankylosis of the sacroiliac joint." (PMID 32021963, 2020).
lupus (8 papers, 2014 to 2025). "For instance, DKK-1 is elevated in the sera and urine samples of systemic lupus erythematosus (SLE) patients, and it is used as a positive biomarker for the identification of active lupus nephritis patients." (PMID 36359340, 2022). "Serum levels of DKK-1, an inhibitor under transcriptional control of Wnt/β-catenin, were also decreased in lupus-prone mice." (PMID 27548498, 2016). "Study on lupus mouse model done also showed a parallel increased levels of Dkk-1 and β-catenin in kidneys." (PMID 24465439, 2014). "Notably, sera collected from mice with proteinuric stage of LN showed strong Wnt inhibitory effects, and the concentration of DKK-1 was comparable to those observed in lupus-prone mice induced apoptosis in tubular and mesangial cells in vitro." (PMID 28373995, 2017). "Similarly, serum samples from lupus patients showed increased levels of DKK1, suggesting altered canonical Wnt signaling in the development of lupus." (PMID 27833613, 2016). "Dysregulation of wingless Wnt signaling has been detected in systemic lupus erythematosus (SLE) patients, and DKK-1 has been proposed as an independent biomarker for bone erosion and even lupus nephritis." (PMID 37841984, 2023). "In another study, significantly more DKK-1 protein was detected in both the serum and urine of SLE patients compared to healthy cohorts, and in particular, the concentration of serum DKK-1 was even higher in SLE patients with lupus nephritis than in those without." (PMID 37841984, 2023). "Serum levels of DKK-1, an inhibitor under transcriptional control of Wnt/β-catenin, did not rise over time in lupus-prone mice as they did in healthy B6 mice." (PMID 27548498, 2016). "For example, using murine models for lupus, it has been shown that Dickkopf-1 (DKK1), a negative regulator of the Wnt/β-catenin pathway, is highly upregulated in the serum during lupus progression." (PMID 27833613, 2016).
pulmonary fibrosis (8 papers, 2020 to 2026). Chronic progressive interstitial lung disorder characterized by the replacement of the lung tissue by connective tissue, leading to progressive dyspnea, respiratory failure, or right heart failure. "In summary, hUSCs exerted multifaceted protective effects against pulmonary fibrosis, at least in part through paracrine mechanisms involving DKK1 and its modulation of Wnt/β-catenin-associated fibrotic responses in MMT." (PMID 42299785, 2026). "Overall, these finding shown that DKK1 inhibitor attenuates PM2.5-induced pulmonary fibrosis in mice." (PMID 33012781, 2020). "The observation that RAB6−/− AEC2s with high colony formation and self-renewal ability was associated with lower expression of DKK1 prompted us to investigate the effect of DKK1 inhibitor on PM2.5-induced pulmonary fibrosis in vivo." (PMID 33012781, 2020). "DKK1 enhanced IL-13-mediated gene expression profiles in pulmonary fibrosis." (PMID 38162655, 2023). "Furthermore, we observed that DKK1 inhibition promotes proliferation, self-renewal and wnt/β-catenin signaling of RAB6 overexpressing AEC2 cells, and attenuates PM2.5-induced pulmonary fibrosis in mice." (PMID 33012781, 2020). "In addition, the authors demonstrated that the excessive expression of Dkk1 prevented pulmonary fibrosis in transgenic mice and that the stimulation of Wnt signalling was induced when fibroblasts, induced by TGF-β, decreased Dkk1 expression." (PMID 32552754, 2020). "Furthermore, DKK1 inhibitors promoted proliferation, self-renewal and wnt/β-catenin signaling of RAB6 overexpressing AEC2 cells, and attenuated PM2.5-induced pulmonary fibrosis in mice." (PMID 33012781, 2020).
androgenetic alopecia (7 papers, 2014 to 2025). "The DKK1 expression level is associated with hair loss; thus, DKK1 inhibition represents an attractive strategy to promote hair growth in androgenetic alopecia." (PMID 38792149, 2024). "DKK1 is widely recognised as a key pathogenic mediator involved in male pattern baldness." (PMID 37991164, 2024). "Recent studies have examined the expression of DKK1 in patients with androgenetic alopecia and AA and have shown significantly higher levels of DKK1 compared with control subjects." (PMID 37991164, 2024). "Previous results have indicated a correlation between the expression of DKK-1 and male pattern baldness." (PMID 38398550, 2024). "In patients with androgenetic alopecia, the expression of AR and DKK-1 in HDPCs within the balding region is higher compared to the non-balding region, inhibiting the Wnt/β-catenin regulatory pathway and resulting in hair thinning." (PMID 38398550, 2024). "The DHT-induced downregulation of DKK-1 expression may represent one of the mechanisms through which NMN mitigates androgenetic alopecia, as implied by the experimental data." (PMID 38398550, 2024). "Particularly, in the case of androgenetic alopecia, ectopic activation of androgen receptor signaling responding to dihydrotestosterone in the HF, mainly in the DP, alters the expression of hair growth-related paracrine factors (such as DKK1, Wnts, and TGF-βs)." (PMID 29761053, 2018). "Specifically, it has been shown that DKK1 expression is upregulated in response to DHT, a known correlate of androgenetic alopecia." (PMID 40497955, 2025). "In androgenetic alopecia, Wnt signaling is known to be inhibited through the action of DHT and DKK1." (PMID 39606918, 2024). "One key factor in non-androgenic male pattern baldness is Dickkopf1 (DKK-1), which promotes catagen." (PMID 24451143, 2014).
Cirrhosis (7 papers, 2013 to 2025). A chronic disorder of the liver in which liver tissue becomes scarred and is partially replaced by regenerative nodules and fibrotic tissue resulting in loss of liver function. "In a large-scale multicenter study (n = 1284), serum DKK1 levels were significantly elevated in patients with HCC compared to those with cirrhosis or chronic HBV infection, which displayed complementary diagnostic potential with AFP." (PMID 40269686, 2025). "Similarly, DKK-1 levels were described to be lower in patients with hepatitis C and cirrhosis as compared to healthy controls in a study from Egypt." (PMID 36230730, 2022). "This may suggest the early secretion of DKK1 in serum in case of cirrhosis as a preneoplastic condition." (PMID 31649806, 2019). "Thus, DKK-1 levels were two-fold lower in patients with cirrhosis (p = 0.002)." (PMID 36230730, 2022). "GP73, MDK and DKK-1 proteins were assessed in 238 individuals divided into 4 groups (HCC, chronic HCV, and chronic HCV with cirrhosis and healthy subjects as a control) Serum levels of GP73, MDK, and DKK-1 were assessed in all subjects by ELISA." (PMID 32198440, 2020). "Furthermore, studies have revealed DKK1 promoter hypermethylation in liver tissue from HCV-infected patients with chronic liver disease and cirrhosis preceding HCC development." (PMID 40269686, 2025). "DKK-1 levels were significantly higher in patients without cirrhosis (n = 9) as compared to patients with cirrhosis (n = 88) (1705 [range, 825–4515] pg/mL versus 888 [range, 199–2313] pg/mL; p = 0.002)." (PMID 36230730, 2022). "The authors retrospectively assessed serum DKK1 in 1284 patients (633 with HCC, 171 with chronic HBV infection, 168 with cirrhosis, and 312 healthy controls) and found that DKK1 has better diagnostic value for HCC than does AFP, especially for patients with AFP-negative and early stage HCC." (PMID 24252133, 2013).
cognitive decline (7 papers, 2018 to 2023). "DKK1 has been shown to be induced by ischemic/hypoxic insults, to be implicated in AD pathogenesis, and to mediate cognitive decline independently of Aβ pathology via inhibition of synaptic transmission." (PMID 35173711, 2021). "Loss of Dkk1 enhances neurogenesis and counteracts the age-related cognitive decline." (PMID 32961703, 2020). "Dkk1 expression increases with age associated to neuronal dysfunction and cognitive decline." (PMID 32961703, 2020). "The observed enhanced working memory and memory consolidation in old mice deficient in Dkk-1 suggests that neutralization of Dkk-1 may be beneficial in counteracting age-related cognitive decline." (PMID 31680933, 2019). "Mouse models suggest that Dkk-1 increases with age and its deletion attenuates age-related cognitive decline." (PMID 31680933, 2019). "Importantly, loss of the Wnt antagonist Dickkopf-1 (DKK1) in adult mice restores AHN, increases dendritic complexity of newborn granule neurons and counteracts age-associated cognitive decline." (PMID 31222184, 2020). "Notably, Dkk1 expression has been found to increase with age, and the knockout of Dkk1 in adult mouse brain has been found to counteract normal age-related cognitive decline through restoration of neurogenesis and increased dendritic complexity." (PMID 30232325, 2018). "DKK1 might constitute the pathological link that independently but synergistically mediates the effects of multifocal microinfarcts and Aβ neuropathology on cognitive decline." (PMID 35173711, 2021). "Our findings suggest that DKK1 expression is potently induced in the brain of male APP/PS1 mice after microinfarcts, which may account for the exaggerated cognitive decline in males." (PMID 35173711, 2021). "Our study suggests that multifocal microinfarcts aggravate cognitive decline more potently in young APP/PS1 male mice compared to young females independently upon Aβ pathology via modulation of various mechanisms that include neurovascular coupling, neuroinflammation, and DKK1 expression." (PMID 35173711, 2021).
hair loss (7 papers, 2021 to 2026). "According to this study, changing the expression of the Wnt signaling pathway gene DKK-1 enhances cell proliferation and transformation, with increased expression in patients with hair loss." (PMID 39202681, 2024). "Excessive production of DHT by SRD5A2, which is a representative cause of male pattern hair loss, induces the expression of DKK1, an inhibitor of the Wnt signaling pathway, via AR stimulation, which ultimately leads to the blockade of the Wnt signaling pathway." (PMID 35784391, 2022). "Adipose‐derived stem cells (ASCs) have shown efficacy in promoting hair growth, while DKK1 inhibits the WNT pathway, which is associated with hair loss." (PMID 37991164, 2024). "We investigated whether targeting Dickkopf 1 (DKK1) and Secreted frizzled-related protein 1 (SFRP1), two AR-regulated genes, offers a novel therapeutic strategy for hair loss." (PMID 41751951, 2026). "Moreover, the AR-DHT complex promotes the transcription of TGF-β1/-β2, and DKK-1, resulting in hair follicle miniaturization, shortened anagen phase, and eventual follicle regression leading to alopecia." (PMID 39000592, 2024). "Besides, LA significantly inhibited Dickkopf-related protein expression (DKK-1), a primary alopecia signaling by dihydrotestosterone." (PMID 33917070, 2021). "Additionally, numerous signaling pathways, including the stimulatory pathways, such as the Wnt/β-catenin, STAT3, and Shh pathways, as well as the inhibitory pathways including Dkk-1, BMP4, and Dickkorpf-related protein are implicated in the treatment of alopecia." (PMID 34099599, 2021).
Hypertension (7 papers, 2014 to 2025). The presence of chronic increased pressure in the systemic arterial system. "The current study aimed to explore the association of serum sclerostin or DKK1 with PAD in patients with hypertension." (PMID 40731833, 2025). "If validated, the results may support the use of circulating sclerostin and DKK1, which can be easily accessed and are noninvasive, as biomarkers for risk stratification in the context of PAD among patients with hypertension." (PMID 40731833, 2025). "sclerostin, and Dkk-1 as independent predictors for LVM, which shows that hypertension is a positive predictor for LVM (with P value <0.01 and confidence interval (CI) = 10.70 to 70.50) and shows also that HDL and s." (PMID 34603797, 2021). "For the inhibitors of the Wnt/β-catenin pathway, serum sclerostin levels, not DKK1, are positively correlated with cfPWV values in patients with hypertension." (PMID 30482161, 2018). "sclerostin, and Dkk-1 as independent predictors for LVMI, which shows that hypertension is a positive predictor for LVMI (with P value =0.050 and CI = −0.025 to 36.80), while serum Dkk-1 was an independent negative predictor for LVMI (with P value < 0.05 and CI = −0.478 to −0.010)." (PMID 34603797, 2021).
ischemic stroke (7 papers, 2020 to 2025). A stroke disorder caused by obstruction of blood flow to the brain, due to thrombotic (local blood clot formation) or embolic (due to a blood clot or other material traveling from another site) event. "Studies indicated that high serum Dkk-1 level is associated with ischaemic stroke and cardiovascular death consistently." (PMID 33081636, 2020). "Similarly, in ischemic stroke, high baseline DKK-1 levels have been linked to a greater mortality and long-term disability." (PMID 40299461, 2025). "Nonetheless, recent evidence is suggesting that the elevated levels of serum Dkk1 at baseline were associated with poor prognosis 1 year after ischemic stroke, suggesting that initial Dkk1 levels in the serum could constitute a biomarker for ischemic stroke prognosis." (PMID 33071819, 2020). "High serum Dkk-1 levels have been consistently reported in patients with ischemic stroke." (PMID 36250025, 2022). "However, the exact causal relationship of DKK1 with the development of coronary artery disease (CAD) and ischemic stroke (IS) remains unclear." (PMID 37742224, 2023). "Importantly, doubleridge mice, which have a reduced basal expression of Dkk1, showed an attenuated reduction of β-catenin and a reduced infarct volume following MCAo, providing a direct proof that Dkk1 contributes to the injury progression in ischemic stroke." (PMID 33071819, 2020). "The functional link between E2 and Wnt pathway via Dkk1 is highly interesting, as it might accounts for the sex-dependent disparities observed in ischemic stroke recovery, thereby constituting a novel target for the development of therapeutic interventions that are tailored for the biological sex." (PMID 33071819, 2020).
metastatic disease (7 papers, 2013 to 2024). "Due to the higher efficacy of Gallocyanine, we further utilized Gallocyanine for determining the effect of DKK1 inhibition on the survival of mice with metastatic disease." (PMID 35296660, 2022). "In our murine dataset, we have not found any mutations in genes published to be associated with metastatic disease like TRKB, NM23, C-MYB, SLUG1, DKK1, NCAM of integrins and selectins." (PMID 29492199, 2018). "Thus, blockade of DKK1 combined with induction of ferroptosis may be a potential therapeutic strategy to limit metastatic disease." (PMID 35296660, 2022). "Thus, pharmacological inhibition of DKK1 might be a potential strategy against metastatic disease." (PMID 35296660, 2022). "Additionally, analysis of TCGA database revealed that expression of DKK1 was elevated in M1 stage compared to M0 stage CRC tissue, and trended to correlate to poor prognosis among metastatic disease." (PMID 31830954, 2019). "Consistently, in the human HCC tissues, the primary tumors showed slightly higher DKK1 expression, compared to those in the adjacent non-tumor liver tissues, moreover, the metastatic tumors showed much higher DKK1 expression in comparison with that in the primary tumors." (PMID 24325363, 2013).
renal osteodystrophy (7 papers, 2013 to 2025). Abnormalities of bone mineral metabolism associated with chronic kidney disease. "In a paracrine signaling manner, rapid decreases of osteocyte genes Sost and likely Dkk1 may represent an adaptive mechanism to maintain effective Wnt signaling as an attempt to delay the initial development of renal osteodystrophy." (PMID 36777346, 2023). "Dkk1, a common Wnt antagonist, was shown to be elevated in patients with CKD-associated bone and mineral disorder and neutralization of Dkk1 by a monoclonal antibody was shown to prevent osteogenic trans-differentiation of VSMCs, VC, and renal osteodystrophy." (PMID 33713163, 2021). "In CKD patients, the correlation of serum Dkk1 with mineral and bone parameters is nonexistent in most studies, suggesting that Dkk1 might have a weak relation with renal osteodystrophy." (PMID 32188018, 2020). "However, serum levels of DKK1 did not correlate with bone histomorphometric parameters and iPTH in patients with renal osteodystrophy." (PMID 31477034, 2019). "We still do not know the real role of Dkk-1 on renal osteodystrophy." (PMID 24236156, 2013).
thyroid cancer (7 papers, 2016 to 2025). "APC2 and DKK1 down-regulate β-catenin by enhancing ubiquitination levels to control the Wnt/β-catenin pathway, thereby promoting the progression of thyroid cancer and decreasing the sensitivity to chemotherapy." (PMID 40028036, 2025). "LSD1 can downregulate the Wnt pathway antagonists APC2 and DKK1 through demethylation in thyroid cancer, thus inhibiting APC2 transcription and activating the HIF-1α/DKK1 axis to regulate cancer progression." (PMID 36059955, 2022). "We further explored whether KDM1A regulated DKK1 expression through the HIF-1α/microRNA-146a axis in thyroid cancer." (PMID 35198054, 2022). "Another study in thyroid cancer cells showed that LSD1 directly regulates APC2 (adenomatous polyposis coli 2) and indirectly promotes the transcription of DKK1 (dikkopf-related protein 1) through HIF1α." (PMID 40028036, 2025). "All these results proved that KDM1A can regulate the transcription of DKK1 via HIF-1α/miR-146a axis; and then activate the Wnt pathway to promote the stemness and chemotherapeutic resistance of thyroid cancer." (PMID 35198054, 2022). "In summary, KDM1A can upregulate the Wnt/β-catenin signaling pathway in thyroid cancer cells by suppressing the ubiquitin-proteasome degradation of β-catenin and its regulation on APC2 and DKK1 may contribute to this process." (PMID 35198054, 2022).